IL6 (interleukin 6)
Diseases named in the same sentence as IL6 in open-access papers (continued):
Sharing a sentence is not in itself a finding about the gene and the disease.
AA amyloidosis (24 papers, 2013 to 2025). Secondary amyloidosis is a form of amyloidosis, that complicates chronic inflammatory disorders (mainly rheumatoid arthritis) and is characterized by the aggregation and deposition of amyloid fibrils composed of serum amyloid A protein, an acute phase reactant. "While colchicine and IL-1 antagonists are effective in AA amyloidosis associated with HPFS6–7; TNF inhibitors, IL-6 antagonists and other b-DMARDs are used in addition to cs-DMARDs in AA amyloidosis associated with RA and other inflammatory diseases for this purpose." (PMID 36128216, 2022). "The introduction and widespread use of biologic DMARDs, especially IL-6 inhibitors, have dramatically reduced the incidence and progression of AA amyloidosis in RA, as demonstrated in both Japanese and international cohorts." (PMID 41517357, 2025). "Interleukin-6 (IL-6) inhibitors have shown promise in preserving renal function, particularly in patients with AA amyloidosis." (PMID 41517357, 2025). "Beyond colchicine, biologic agents such as anakinra (IL-1 receptor antagonist) and tocilizumab (IL-6 inhibitor) have shown promise in treating secondary amyloidosis in systemic autoinflammatory diseases, including SJIA." (PMID 40630350, 2025). "A central role for interleukin 6 (IL-6) in the pathogenesis of AA amyloidosis has been suggested, because IL-6 is a critical inducer of SAA." (PMID 37026007, 2023). "Biologic drugs for RA have been used in patients with secondary AA amyloidosis, including tumor necrosis factor and Janus kinase inhibitors, interleukin 6 blockers, and a T cell modulator." (PMID 34397890, 2021). "Here, we report that anti-IL6 therapy abrogated uncontrolled symptoms of secondary AA amyloidosis in the GI tract of a patient with RA." (PMID 34397890, 2021). "As IL-6 is one of the important drivers of SAA release, it is conceivable to consider blocking of IL-6 signaling in AA amyloidosis." (PMID 33981717, 2021). "IL-6 is required for the production of the amyloid A protein in the liver; thus, IL-6 inhibition is thought to be effective for amyloid A amyloidosis." (PMID 30423923, 2018). "Notably, IL-6 inhibitors have demonstrated greater efficacy than TNF inhibitors in managing AA amyloidosis, as IL-6 is directly involved in stimulating SAA production." (PMID 40700073, 2025). "Recently there are few reports pointing out that tocilizumab(TCZ), an anti IL-6 agent may be effective in AA amyloidosis resistant to conventional treatments." (PMID 28558744, 2017). "IL-6 plays a central role in inflammation, SAA production, and subsequent amyloid deposition in AA amyloidosis." (PMID 41517357, 2025). "Interleukin-6 (IL-6) is one of the drivers of SAA release and effectiveness of the humanized anti-IL-6 receptor antibody tocilizumab (TCZ) for the treatment of AA amyloidosis has been observed in some rheumatic conditions." (PMID 33981717, 2021). "A number of recent studies have verified that therapeutic strategies involving IL-6 inhibitors and TNFα inhibitors result in a decrease of serum SAA level and consequently represent an excellent therapeutic strategy for AA amyloidosis." (PMID 33679725, 2020). "Prior reports have shown that excess IL-6 in UCD and iMCD can lead to increased transcription of SAA and the development of AA amyloidosis as a rare complication." (PMID 32028407, 2020). "IL-6 inhibition may result in the suppression of SAA levels, improvement of the clinical symptoms of AA amyloidosis, and regression of intestinal AA fibril deposition." (PMID 37026007, 2023). "Beyond colchicine, new monoclonal antibodies such as IL-1 inhibitors anakinra and canakinumab, and anti-IL-6 tocilizumab may represent a key in optimizing FMF treatment and prevention or control of AA amyloidosis." (PMID 34684086, 2021). "Inhibiting IL-6 is reasonable in AA amyloidosis but, to the best of our knowledge, experience of TCZ has not previously been published in patients with AS." (PMID 33981717, 2021).
AA amyloidosis (continued). "Indeed, proinflammatory cytokines (IL-1β, IL-6, and TNF-α) produced by antitumor lymphocytes or macrophages can induce SAA production and development of AA amyloidosis." (PMID 24558629, 2013). "Notably, significantly elevated levels of IL-6 and/or TNF-α may play a role in the onset of AA amyloidosis." (PMID 41374422, 2025). "As trials for IL-6 blocking agents like TCZ and sarilumab did not meet their primary endpoints in AS, the approach of initially adding a TNF-blocking agent in those AS patients who develop AA amyloidosis seems rational." (PMID 33981717, 2021).
abortion (24 papers, 2010 to 2025). the ending of pregnancy by removing a fetus or embryo before it can survive outside the uterus. "Increased levels of IL‐6 have been reported in women with recurrent pregnancy loss and in a murine abortion model, a reduction in the embryo resorption rate by amniotic mesenchymal stem cells was accompanied by a decrease in IL‐6 expression." (PMID 39460389, 2024). "Using a similar mouse model, Blois and colleagues adoptively transferred syngeneic BMDCs into abortion-prone females and showed a significant reduction in fetal resorption, which was associated with decreased serum IL-6 levels." (PMID 27895621, 2016). "This study has proven a possible association of polymorphism -819 C/T and the increased frequency of recurrent abortions and the lack of association between polymorphisms IL10-592C/A, -1082A/G, IL6-174G/C and the abortion disease in the studied group." (PMID 25469134, 2014). "-B. abortus 2308 infection induces a decrease in progesterone synthesis by the placenta, resulting in higher intracellular survival, placentitis values (IFN-γ and IL-6 production), and abortion induction due to the inflammatory role of progesterone." (PMID 38792696, 2024). "Analysis of the relationship between cytokines and human chorionic gonadotropin showed significantly higher Il-6/β-hCG ratios in women with spontaneous abortion." (PMID 34444287, 2021). "They found IFN-γ, TNF-α, IL-2, IL-6 and IL-17A cytokines were significantly increased in spontaneous abortion ((SA) group and recurrent miscarriage (RM) group (Ctinfected) versus controls." (PMID 35392343, 2021). "Next factors that can also be considered when predicting the risk of spontaneous abortion are SNPs in TLR2, TLR4, IL-6, IL-8, and PGR genes." (PMID 30116270, 2018). "This drop is significant in preventing abortion, as IL-6 release stimulates prostaglandin synthesis by uterine tissues." (PMID 20161765, 2010). "Similarly to the data obtained from our analysis, previous studies described increased serum levels of TNF-α and IL-6 levels in patients with spontaneous abortion than in women with normal pregnancies." (PMID 35955896, 2022). "Our previous studies showed that serum IL-6 in ACA-positive pregnant mice at risk of spontaneous abortion was significantly increased, but there were no changes in the placental or decidual IL-6 levels." (PMID 33414834, 2020). "On the other hand, VEGF-A, estrogen receptors a and ß, and inflammatory cytokine levels such as IFN?, IL-1ß and IL-6, which are also known as risk factors of contributing to abortion, were not changed in Tet-mev-1 mice." (PMID 24936442, 2014). "It has been reported that the VEGFA expression decreases in the endometrial tissue of patients with idiopathic recurrent abortion during the peri-implantation period, which may be related to the downregulation of angiogenic cytokines, including IL-2, IL-6, and IL-8." (PMID 40585325, 2025). "For instance, demonstrated that levels of IL5, IL6, IL1-ß, TNF-α, TLR4, and Tollip were significantly up-regulated in ewes affected with abortion than in resistant ones, while SOD and CAT gene patterns elicited an opposite trend." (PMID 40872670, 2025). "The results showed that the mean plasma level of IL-1β, IL-6 and TNF-α in repeated abortion were markedly higher than those in control group." (PMID 30061639, 2018). "Experimentally infected mares expressed more IL-6, IL-8, IL-1β, and TNF-α mRNA in the cervical star region and produced high concentrations of PGE2 and PGF2α in allantoic fluid, leading to abortion or birth of a precociously mature foal." (PMID 23390521, 2013). "While it decreases the levels of proinflammatory cytokines such as progesterone, IL-6, and TNF-α, which are frequently used in the treatment of threatened abortion, it increases the levels of the anti-inflammatory cytokine IL-10 in proportion to the administered dose." (PMID 34909296, 2021).
abortion (continued). "In normal pregnancy, the levels of serum Th2 cytokines IL-6 and IL-10 were found to be significantly higher than in patients with recurrent spontaneous abortion, while levels of serum Th1 cytokine IFN-γ is significantly elevated in recurrent spontaneous abortion." (PMID 31649614, 2019).
anaphylaxis (24 papers, 2011 to 2025). An acute hypersensitivity reaction that occurs from exposure to an allergen. "Recent evidence indeed suggested that elevated IL-6 is a diagnostic marker of systemic anaphylaxis in human food allergy in general." (PMID 36238931, 2022). "Hence, patients with active disease characterized by high IL‐6 levels may be susceptible to developing anaphylaxis." (PMID 40626088, 2023). "Thus, IL-6 and the chemokines identified in this model may be considered for investigation as potential diagnostic markers of anaphylaxis caused by wheat ingestion in humans." (PMID 36238931, 2022). "Increased concentrations of IL-6 have also been measured in other systemic mastocytosis patients and uniphasic classical anaphylaxis." (PMID 40299000, 2025). "C-reactive protein, IL6, and KC concentrations were significantly higher in the critical illness group, compared to the anaphylaxis (CRP P < 0.0001, IL6 P < 0.001, KC P = 0.015) and healthy groups (CRP P < 0.0001, IL6 P < 0.0001, KC P < 0.0001)." (PMID 36003410, 2022). "The authors also demonstrated selective elevation of IL-6 upon oral allergen challenge, suggesting it has a key role in eliciting anaphylaxis via the oral route." (PMID 36276818, 2022). "For instance, in response to cytokines such as Interleukin-1, Interleukin-6, Tumor necrosis factor-α or Interferon-γ (most of them are mediators of anaphylaxis)." (PMID 34248989, 2021). "A recent study comparing baseline and reaction samples in perioperative anaphylaxis revealed IL-6 and CCL2 as potential biomarkers." (PMID 34575019, 2021). "Consistently, serum levels of pro-inflammatory cytokines TNF-α and IL-6 were elevated in C48/80-induced anaphylaxis mouse models but were significantly reduced by treatment with DXM." (PMID 34737708, 2021). "Inflammatory cytokine biomarkers, such as TNF-α, IL-6, and IL-1β, can be increased in serum of patients with anaphylaxis and cytokine storm-like reactions, but their sensitivity or specificity is still not demonstrated." (PMID 34575019, 2021). "The levels of TNF-α and IL-6 in peritoneal fluid decreased in the Ang-1-treated mice anaphylaxis model." (PMID 24586553, 2014). "The expressions of interleukin 10 (IL‐10) and IL‐6 were significantly increased during anaphylaxis in patients with cystic echinococcosis, according to previous studies, and IL‐10 and IL‐6 play a crucial role in the occurrence and development of a variety of inflammatory diseases." (PMID 37647453, 2023). "Another study performed to characterize serum biomarkers during anaphylaxis in the emergency department patients identified elevated IL-6 and IL-10 levels, which could be a unique signature of anaphylaxis." (PMID 34575019, 2021). "To determine if the decrease in MC numbers had an effect on function, we performed a passive systemic anaphylaxis assay and observed that Il9ΔCNS-25 mice had significantly less temperature change (area under the curve, p = 0.043) and significantly less serum IL-6 at the termination of the assay." (PMID 30442929, 2018). "Similarly, patients with both pyrogenic reactions and anaphylaxis had significantly higher peak concentrations of IL-6, IL-10, TNFα and sTNFRI compared to patients with severe anaphylaxis alone." (PMID 23936562, 2013). "In patients who had anaphylaxis, concentrations of IL-6 and IL-10 remained elevated for up to 24 hours after the initial dose of antivenom, whereas concentrations of TNFα and sTNFRI returned to baseline levels between 10–15 hours after the initial dose of antivenom." (PMID 23936562, 2013). "Second, our experiment showed the IP IOP administration could decrease the proinflammatory cytokines of TNF and IL-6 and oxidative stress, but includes no data demonstrating the lower risk of anaphylaxis and hypersensitivity." (PMID 37376162, 2023).
anaphylaxis (continued). "For example, many dogs with anaphylaxis showed increased plasma IL-10 concentration, known to increase within an hour of shock or endotoxaemia, and some dogs showed elevated plasma IL-6 or CCL2, known to increase within 1–3 h of shock, endotoxaemia or surgical stimulus." (PMID 36003410, 2022). "Based on fold-change analyses, we identified four immune markers (IL-6, IL-9, IL-17E, MIP-3a) that were of high importance (4–5.9-fold or higher) during anaphylaxis." (PMID 38139075, 2023). "Therefore, Egr3 may increase expression levels of IL-6 and IL-8 during anaphylaxis via NF-κB." (PMID 34234781, 2021). "In the present study, roxatidine decreased mRNA levels of TNF-α, IL-6, and IL-1β in PMACI-stimulated HMC-1 and the serum of anaphylactic shock animal models." (PMID 28139747, 2017). "Also, anti-T20 protected OVA allergic mice from PGN-induced lethal anaphylaxis, and the serum levels of TNF-α, IL-6, and LTC4 of anti-T20 treated PGN-challenged OVA allergic mice were decreased as compared to isotype control of anti-T20 treated mice." (PMID 27213155, 2016). "In contrast, the anaphylaxis group did not have significantly higher concentrations of these three biomarkers, compared to the healthy group (CRP P = 0.99, IL6 P = 0.17, KC P = 0.08)." (PMID 36003410, 2022). "In addition, the selective elevation of IL-6 and a small panel of chemokines (CCL5, CCL20, CCL22, and CXCL1) in the spleen upon oral allergen but not saline challenge suggests their key role in eliciting anaphylaxis via the oral route." (PMID 36238931, 2022).
Aortic dissection (24 papers, 2012 to 2025). Aortic dissection refers to a tear in the intimal layer of the aorta causing a separation between the intima and the medial layers of the aorta. "The association between interleukin-6 (IL-6) and the pathology of aortic dissection has been demonstrated in numerous basic studies." (PMID 37636294, 2023). "Comparing inflammatory biomarkers in a cohort of patients with type B acute aortic dissections, IL-6 was reported to significantly increase within 24 h only in patients who developed PIS." (PMID 36292200, 2022). "IL-6 was found to increase in acute aortic dissection, and when downregulating IL-6 expression, vascular macrophages production were decreased, thus delaying the occurrence of aortic dissection." (PMID 33869300, 2021). "This study is to explore the relationship between the function and number of EPC and aortic dissection detection risk score (ADD-RS) in AAD and hypertensive patients and analyze the level of IL-6 and IL-17 in the two groups." (PMID 33869300, 2021). "A large number of basic studies have shown that interleukin-6 (IL-6) is related to the pathology of aortic dissection." (PMID 32677975, 2020). "A large number of cytokines have also been found infiltrating the aortic wall of patients with aortic dissection, such as IL-6 and IL-17." (PMID 32778051, 2020). "The sensitivity and specificity of IL-6 > 108 pg/mL for early adverse prognosis after acute aortic dissection were 91.2 and 89.7%, respectively (95% CI 0.839 to 0.963)." (PMID 32677975, 2020). "These inflammatory mediators (IL-6 and TNF-α), along with proteases like matrix metalloproteinases (MMPs), can disrupt the structural integrity of the aortic wall, thus increasing the risk of aortic dissection progression." (PMID 41567381, 2025). "IL-6 was reported to be related to the severity of aortic dissection and the time of presentation." (PMID 36712253, 2022). "Moreover, p62, IL-6, Rab7, and Atg5/IRE1α pathways of autophagy may play a role in aortic aneurysm and aortic dissection, and can be considered a novel super-selective therapeutic target." (PMID 34754985, 2021). "Positive correlation between aortic dimensions and IL-6 or TIMP-1 was seen even after excluding patients with past aortic dissection, suggesting that associations between aortic dimensions and IL-6 or TIMP-1 are to some extent independent of former dissection or surgical manipulation." (PMID 30883599, 2019). "A number of studies found that blood or lung tissues from aortic dissection and thoracic aortic aneurysm patients with postoperative ALI showed significant increases in C-reactive protein (CRP), interleukin-6 (IL-6), and monocyte chemoattractant protein-1 (MCP-1)." (PMID 37636294, 2023). "In addition to CXCL1 and G-CSF, multiple other cytokines and chemokines, including IL-6 and MCP-1, have been reported to play a role in the local and systemic inflammatory responses after acute aortic dissection." (PMID 32027731, 2020). "In 21 patients with past history of aortic dissection, circulating IL-6 was significantly higher than in patients without dissection (median 2.6 pg/ml IQR 1.8–5.2 vs median 1.1 pg/ml IQR 0.3–2.4, p = 0.001 respectively)." (PMID 30883599, 2019).
Behçet's disease (24 papers, 1992 to 2025). "Upon stimulation with recombinant (r)IL-37, DCs from patients with Behcet’s disease (BD) have decreased IL-6 and IL-1β expression, and increased IL-27 expression." (PMID 29137646, 2017). "This can explain how the levels of both serum GM-CSF and serum IL-6 were found to be high in Behcet's disease as reported by different studies." (PMID 25759827, 2014). "Both TNF-α and IL-6 have been found elevated in aqueous humour of patients with idiopathic uveitis, Behcet's disease and Fuchs' heterochromic cyclitis." (PMID 20467456, 2010). "Notably, one study showed that PBMCs from Behçet’s disease patients had higher levels of IFNγ and IL-6 secretion compared to controls upon interphotoreceptor retinoid-binding protein (IRBP) and S-antigen stimulation." (PMID 39867889, 2024). "Furthermore, it has been demonstrated that, in comparison to healthy controls, the monocytes from Behçet’s disease patients produce higher levels of IL-1β, IL-6, and TNF-α." (PMID 38674208, 2024). "A presumable significance of IL-6 in the development of TA could be shown by analyzing peripheral blood mononuclear cells (PBMC) from TA patients which produced more IL-6 upon stimulation than their counterparts from individuals with Behçet's disease." (PMID 31244756, 2019). "Behcet’s disease (BD) is characterized by systemic recurrent inflammation with increased production of tumor necrosis factor (TNF)–α and interleukin (IL)-6 by peripheral blood mononuclear cells (PBMCs)." (PMID 27441030, 2016). "Interleukin-6, a potent pro-inflammatory cytokine, might be involved in Behçet's disease (BD) pathological pathways." (PMID 18475474, 1992). "Although the patient had a history of Behçet's disease, CNS symptoms were not noted in her medical history, and IL-6 levels in the CSF were normal." (PMID 39618746, 2024). "It is known that JAK1/STAT3 signaling pathway is activated in some systemic vasculitides (Behcet disease) through the activation of Th1/Th17-type cytokines such as IL-2, interferon (IFN-γ), IL-6, IL-17, and IL-23 but its role in KD is not well-understood." (PMID 33692975, 2021).